CDK9 (cyclin dependent kinase 9)
Diseases named in the same sentence as CDK9 in open-access papers (continued):
Sharing a sentence is not in itself a finding about the gene and the disease.
chordoma (continued). "In this study, we show CDK9 is related to poor outcomes and promotes chordoma progression and inhibits apoptosis by regulating RNAP II and apoptosis-related proteins." (PMID 31892980, 2020). "The effect of CDK9 inhibition on chordoma cells was further evaluated with a three-dimensional (3D) cell culture model which mimics the in vivo environment." (PMID 31892980, 2020). "We found inhibition of CDK9 in chordoma cell lines to decrease p-RNAP II Ser-2 and Mcl-1 while also suppressing proliferation and inducing apoptosis." (PMID 31892980, 2020). "The CDK9 protein was localized in the nucleus in both chordoma cell lines, which is consistent with the chordoma tissue IHC results." (PMID 31892980, 2020). "In the present study, we show CDK9 is aberrantly expressed in chordoma cell lines and tumor tissues." (PMID 31892980, 2020). "The average CDK9 expression for patients with primary versus locally recurrent chordomas was statistically significant as well, at 2.25 and 3.29, respectively (p= 0.0144)." (PMID 31892980, 2020). "The functional roles of CDK9 in chordoma were investigated after the addition of small interfering RNA (siRNA) and CDK9 inhibitor (LDC000067)." (PMID 31892980, 2020). "To verify the roles of CDK9 in chordoma cell growth and proliferation, we conducted a knockdown analysis using CDK9 specific siRNA." (PMID 31892980, 2020). "We successfully established 3D spheroids of chordoma cells and found that CDK9 inhibition significantly diminishes chordoma spheroid growth." (PMID 31892980, 2020). "CDK inhibitors such as THZ1, NVP-2 and THZ531 that inhibit CDK7, CDK9, CDK12 and CDK13, respectively, have been shown to downregulate SE-related oncogene expression and promote DNA damage response gene loss in chordoma and acute T-lymphoblastic leukaemia cells, respectively." (PMID 35514959, 2022). "We also show knockdown and inhibition of CDK9 decreases chordoma cell proliferation and growth." (PMID 31892980, 2020). "Taken together, these results support CDK9 as an emerging potential target in chordoma therapy." (PMID 31892980, 2020). "High- expression of CDK9 correlated with recurrence and poor outcomes for chordoma patients." (PMID 31892980, 2020). "The CDK9 protein was predominantly localized within the nucleus of chordoma cells." (PMID 31892980, 2020). "Collectively, the decrease in Mcl-1 and Survivin reasonably explains how inhibition of CDK9 may induce apoptosis in chordoma cell lines." (PMID 31892980, 2020). "It is well accepted that cyclin-dependent protein kinase 9 (CDK9) has tumorigenic roles in various cancers; however, the expression and significance of CDK9 in chordoma remains unknown." (PMID 31892980, 2020). "Downregulation of Mcl-1 was also observed in the CDK9 siRNA transfected chordoma cells." (PMID 31892980, 2020). "Overall, these results support targeting CDK9 as a potential strategy in chordoma therapy." (PMID 31892980, 2020). "It seems likely, therefore, that CDK9 expression may feature more prominently in recurrent chordoma tumorigenesis." (PMID 31892980, 2020). "Significant differences between chordoma and normal tissue were identified for three kinases: Aurora kinase A (AURA), Cyclin-dependent kinase 9 (CDK9) and MAPK/MAK/MRK overlapping kinase (MOK)." (PMID 37197427, 2023). "Second, to evaluate the roles of AURA, CDK9, and MOK in chordoma cell proliferation, we silenced AURA, CDK9, and MOK protein expression in chordoma cell lines using siRNAs, and demonstrated that knockdown efficacy to be over 70% in JHC7 cells (–F)." (PMID 36248973, 2022). "Despite the slow growth of chordoma cells, JHC7 proliferation rate after knockdown of AURA, CDK9, and MOK was nevertheless significantly suppressed relative to control cells as measured by CCK8 assay (–I)." (PMID 36248973, 2022). "However, the function and therapeutic potential of CDK9 in chordoma have not been elucidated." (PMID 31892980, 2020).
atherosclerosis (6 papers, 2016 to 2022). A disease characterized by the build-up of fatty material and calcium deposition in the arterial wall resulting in partial or complete occlusion of the arterial lumen. "In this study, inflammation and phenotypic switching of VSMCs were observed in HFD-induced atherosclerosis in ApoE-/- mice, which were accompanied with increased CDK9 in the serum and atherosclerotic lesions where it colocalized with VSMCs." (PMID 34102609, 2021). "The results demonstrated that treatment with pharmacological CDK9 inhibitor alleviated atherosclerosis by reducing CDK9 phosphorylation and then inhibiting inflammation and phenotypic switching of VSMCs." (PMID 34102609, 2021). "In animal experiments, the development of atherosclerosis was accompanied by the proliferation of VSMCs, and the increase in the number of VSMCs leads to the increase in CDK9 protein level." (PMID 34102609, 2021). "This study was to explore the pharmacological role of CDK9 inhibition in attenuating atherosclerosis." (PMID 34102609, 2021). "Next, LDC000067 was applied to the ApoE-/- mice to explore the potential role of CDK9 in atherosclerosis." (PMID 34102609, 2021). "Cyclin-dependent kinases 9 (CDK9), a potential biomarker of atherosclerosis, was significantly increased in coronary artery disease patient serum and played an important role in inflammatory diseases." (PMID 34102609, 2021). "Medicinal chemists should start to modify LDC000067 to explore new CDK9 inhibitors with low toxicity for the treatment of atherosclerosis." (PMID 34102609, 2021). "Altogether, These findings indicate that CDK9 represent an important role for inflammation in the pathogenesis of atherosclerosis." (PMID 26636538, 2016). "Additionally, lncRNA PEBP1P2 has also presented beneficial protective effects against abnormal VSCM proliferation and atherosclerosis, mainly by targeting the cyclin-dependent kinase 9 (CDK9) pathway." (PMID 35563540, 2022). "Therefore, we conclude that CDK9 in VSMCs plays an important role in the pathogenesis of atherosclerosis." (PMID 34102609, 2021). "The CDK9 level was increased in the serum of patients with atherosclerosis and could be a potential biomarker of atherosclerosis." (PMID 34102609, 2021). "Whether CDK9 regulating leukocyte-endothelial interaction also has an important role in atherosclerosis needs to be further investigated in the future." (PMID 34102609, 2021). "It has been reported that CDK9 was highly increased in the serum of patients with atherosclerosis." (PMID 34102609, 2021). "CDK9 (Cyclin-dependent kinase 9)/Cyclin T1/RNA polymerase II pathway has been demonstrated to promote the development of several inflammatory diseases, such as arthritis or atherosclerosis, however, its roles in allotransplantation rejection have not been addressed." (PMID 27102157, 2016). "Moreover, the CD14+ cells showed increased CDK9 levels in atherosclerotic plaques, which indicated the role of CDK9 in monocyte infiltration during atherosclerosis." (PMID 26636538, 2016). "Therefore, firstly the CDK9 level in the mouse atherosclerosis model was analyzed." (PMID 34102609, 2021). "However, the role of CDK9 in atherosclerosis is incompletely illuminated, and it remains unclear if pharmacological inhibition of CDK9 can be developed as a therapeutic strategy for atherosclerosis." (PMID 34102609, 2021). "In this study, atherosclerosis model was established in apolipoprotein E null mice (ApoE-/-) fed with high fat diet (HFD), and a highly specific small-molecule CDK9 inhibitor, LDC000067, was utilized to treat the atherosclerotic mice." (PMID 34102609, 2021). "CDK9 inhibitor LDC000067 treatment significantly suppressed HFD-induced inflammation, cell proliferation and phenotypic switching of VSMCs resulting in reduced atherosclerosis in the ApoE-/- mice, which were further confirmed in vitro using ox-LDL-treated human VSMCs." (PMID 34102609, 2021).
atherosclerosis (continued). "Treatment with CDK9 inhibitor LDC000067 dramatically reduced hyperlipidemia-induced inflammation and phenotypic switching of VSMCs and ultimately prevented atherosclerosis progress without changing serum lipid levels, indicating that CDK9 may be a new target for the prevention of atherosclerosis." (PMID 34102609, 2021).
B-cell lymphoma (6 papers, 2016 to 2022). "The effect of dinaciclib on MYC level through inhibition of CDK9 in MYC-driven tumor cells was reported previously in a study of B cell lymphoma cell lines." (PMID 27486754, 2016). "Furthermore, CDK9 inhibition by dinaciclib treatment has been shown to induce apoptotic responses in aggressive MYC-driven B-cell lymphoma through transcriptional blockage of MCL-133." (PMID 28361959, 2017). "Altogether, our data show that 9-ING-41 results in increased apoptosis and decreased proliferation in aggressive B-cell lymphoma cells and enhances the antitumor effects of BCL-2 and CDK-9 antagonists." (PMID 29383130, 2017).
gastric cancer (6 papers, 2019 to 2025). A primary or metastatic malignant neoplasm involving the stomach. "In a mouse model of orthotopic gastric cancer, M@BP can effectively target and accumulate in gastric cancer cells, blocking the activation of CDK9 and BRD4 and impeding the growth of gastric cancer cells." (PMID 40190709, 2025). "Dual luciferase reporter activity demonstrated that miR-613 directly targets the CDK9 gene for its downregulation and suppresses the metastases and progression of gastric cancer cells." (PMID 36769170, 2023). "In human gastric cancer cells PIN1 induces a conformational change of phosphorylated BRD4 supporting its interaction with CDK9, thus improving BRD4-mediated gene expression relevant for gastric cancer cell proliferation and tumor development." (PMID 30873382, 2019). "CDK9 was present, to a smaller extent, in breast, lung, prostate and gastric cancer." (PMID 35249548, 2022). "CDK9 is another type of CDK that is upregulated in gastric cancer, and is regulated via the activity of miR-613, which functions as a tumor suppressor in gastric cancer cells." (PMID 36769170, 2023).
acute leukemia (5 papers, 2016 to 2022). A clonal (malignant) hematopoietic disorder with an acute onset, affecting the bone marrow and the peripheral blood. "MLL fusions and the FLT3-ITD mutation are known oncogenic drivers of acute leukemias and are dependent on the activity of CDK9 and FLT3, respectively." (PMID 35267421, 2022). "The transcriptional changes mediated by the BET degrader in ABC DLBCL cells correlate with that induced by CDK9 inhibitors, in line with results available in acute leukemias." (PMID 36046113, 2021). "AFF family members, which are frequently fused to MLL in acute leukemias, are also part of the super elongation complex, thus mis-localizing CDK9 to HOX gene promoters and inducing abnormal CDK9 expression, cell growth, and proliferation." (PMID 34065376, 2021). "Because CDK9 was significantly increased in atherosclerotic patients and has been shown to be inhibited by FLA, the physiological properties of CDK9 treated with FLA were further investigated in THP-1 cells (human monocytic acute leukemia cell line)." (PMID 26636538, 2016).
Ewing sarcoma (5 papers, 2020 to 2024). A small round cell tumor that lacks morphologic, immunohistochemical, and electron microscopic evidence of neuroectodermal differentiation. "After, we summarize the data on CDK9 inhibition in a group of rare pediatric solid tumors such as rhabdomyosarcoma, Ewing’s sarcoma, synovial sarcoma and malignant rhabdoid tumors (soft tissue sarcomas), highlighting the more recent results in this field." (PMID 32903585, 2020). "Combined treatment of Ewing sarcoma with BRD- and CDK9-inhibitors resulted in enhanced responses compared to individual drugs in vitro and in a preclinical mouse model in vivo." (PMID 38255982, 2024). "Combined treatment of Ewing Sarcoma with BRD- and CDK9-inhibitors resulted in enhanced responses compared to individual drugs not only in vitro but also in a preclinical mouse model in vivo." (PMID 35883603, 2022). "In Ewing Sarcoma, co-immunoprecipitation revealed an interaction of BRD4 with CDK9." (PMID 35883603, 2022). "The CDK-9 inhibitors alvocidib and SNS-032 have shown effective in treating Ewing sarcoma cells." (PMID 35580047, 2022). "Thus, recent studies have found that the combination of MTM with CDK9 inhibitors or the semisynthetic taxane cabazitaxel resulted in improved anti-tumor activity and/or limited MTM-toxicity in Ewing sarcoma and B-cell acute lymphoblastic leukemia, respectively." (PMID 33806182, 2021).
glioma (5 papers, 2018 to 2024). A benign or malignant brain and spinal cord tumor that arises from glial cells (astrocytes, oligodendrocytes, ependymal cells). "The related mechanism shows that in glioma, PRMT6 is recruited by the transcriptional regulator CDK9 to the YTHDF2 promoter region and then synergistically promotes the transcriptional activation of YTHDF2 with CDK9." (PMID 38637831, 2024). "For example, high CDK7 expression is associated with favorable prognosis in adrenocortical carcinoma (ACC) and high CDK9 expression with favorable prognosis in pancreatic adenocarcinoma (PAAD) and low-grade glioma (LGG)." (PMID 36577800, 2022). "In glioma models in female mice, a BET inhibitor enhances the oncolytic activity of oHSV by impeding IGF2BP3-induced NETosis, reinforcing virus replication through BRD4 recruitment with the CDK9/RPB-1 complex to HSV gene promoters." (PMID 38167409, 2024). "In addition to inhibiting CDK7, SNS-032 also inhibits the cyclin-dependent kinases CDK2, CDK5 and CDK9, however, even though SNS-032 can alter glioma response to hypoxia, it is not toxic toward U87 cells even at very high drug concentrations (500 nM)." (PMID 29844863, 2018).
liver cancer (5 papers, 2019 to 2025). An epithelial or non-epithelial malignant neoplasm that arises from the liver. "In the current study, we show that CDK9 inhibition by dinaciclib and alvocidib impeded short-term and long-term proliferation and induced apoptosis in high-risk pediatric liver cancer models." (PMID 37729391, 2024). "First, they establish that on-target inhibition of CDK9 can have potent antitumor effects against genetically defined autochthonous liver cancers in vivo, leading to improved liver function and prolonged survival." (PMID 35442775, 2022).
non-small cell lung carcinoma (5 papers, 2014 to 2022). A group of at least three distinct histological types of lung cancer, including non-small cell squamous cell carcinoma, adenocarcinoma, and large cell carcinoma. "Since inhibitors of cyclin-dependent kinase 9 are undergoing clinical trials for hematological malignancies, our studies suggest that these inhibitors would be attractive candidates to combat non-small cell lung cancer." (PMID 34359807, 2021). "Data matrices were generated by measuring anti-proliferative effects (IC50) of i-CDK9 and JQ1 as a single agent or in combination on both HeLa and H1792, a non-small cell lung cancer cell line with significant MYC amplification (CN = 8)." (PMID 26083714, 2015). "When evaluating cancer selectivity of TRAIL combined with SNS-032, the most selective and clinically used inhibitor of CDK9, we found that a panel of mostly TRAIL-resistant non-small cell lung cancer cell lines was readily killed, even at low concentrations of TRAIL." (PMID 24362439, 2014).
Arthritis (4 papers, 2012 to 2021). Inflammation of a joint. "In fact, CDK9 inhibition has been investigated as an anti-inflammatory therapeutic approach for inflammatory conditions, such as arthritis, since CDK9 inhibition was shown to increase the percentage of regulatory T cells in spleens from arthritic mice." (PMID 34207158, 2021). "When we treated CIA mice with specific CDK9 inhibitors, we observed a marked improvement in the clinical signs of arthritis." (PMID 27511630, 2016). "(ii) CDK9 inhibition (solely by flavopiridol) has as yet only been tested in two inflammatory in vivo models (arthritis, hepatitis)." (PMID 22571657, 2012). "Perhaps surprisingly, the authors did not describe CDK9 as another potential target of flavopiridol in arthritis." (PMID 22571657, 2012).